FEZF1-AS1 (FEZF1 antisense RNA 1)
Gene: Long non-coding RNA gene on chromosome 7 (122,303,658 to 122,310,119, forward strand). Ensembl gene ENSG00000230316.
Diseases named in the same sentence as FEZF1-AS1 in open-access papers:
FEZF1-AS1 is named in the same sentence as 4 diseases in open-access papers, as found by Europe PMC text mining. Sharing a sentence is not in itself a finding about the gene and the disease. The quoted sentences say what the papers report.
gastric cancer (1 paper, 2021). A primary or metastatic malignant neoplasm involving the stomach. "In another study, FEZF1 antisense RNA 1 (FEZF1-AS1) recruited demethylase LSD1 to the promoter of p21 and reduced the H3K4 m2 level, resulting in the repression of p21 expression in gastric cancer." (PMID 33428595, 2021).
retinoblastoma (1 paper, 2021). A malignant tumor that originates in the nuclear layer of the retina. "LncRNA FEZF1 antisense RNA 1 (FEZF1-AS1) has been found to stimulate retinoblastoma." (PMID 33432525, 2021).
tumor (1 paper, 2019). "Long non-coding RNA (lncRNA) FEZF1 antisense RNA 1 (FEZF1-AS1) has been shown to be up-regulated in tumor tissues and cells, and exerts oncogenic effects on various types of malignancies." (PMID 31076545, 2019).
FEZF1-AS1 also shares sentences with these, for which no sentence is quoted: cancer (1 paper).